TNF (tumor necrosis factor)
Diseases named in the same sentence as TNF in open-access papers (continued):
Sharing a sentence is not in itself a finding about the gene and the disease.
Arthritis (continued). "Consistent with this, it inhibited TNF-α production in RA synovial explants and reduced bone loss in murine collagen-induced arthritis." (PMID 24771982, 2014). "Treatment was initiated 6 hours after LPS challenge when the release of TNFα associated with LPS had subsided and before arthritis symptoms were manifest." (PMID 25344414, 2014). "These animals develop spontaneous and progressive arthritis from about 3 weeks of age demonstrating that pathology associated with TNFα in RA can be recapitulated in the mouse." (PMID 25344414, 2014). "Membrane-associated TNFα is biologically active and provides sufficient activity to induce arthritis in a transgenic model displaying synovial hyperplasia and inflammation." (PMID 24204798, 2013). "IL-1β and TNF-α are associated with the development of early arthritis, whereas IL-1β maintains the inflammatory reaction in later stages." (PMID 23597113, 2013). "A pathogenic factor in the development of arthritis is inflammation driven by proinflammatory cytokines, especially TNF, IL-1β, IL-6, and IL-17." (PMID 24286140, 2013). "TTP deficiency is associated with cachexia, arthritis, autoimmunity, and myeloid hyperplasia, secondary to increased TNF-α and GM-CSF levels." (PMID 22315682, 2012). "We believe that one of the mechanisms underlying the attenuation of arthritis development by SA13353 is inhibition of TNF-a production by inflammatory cells exposed to neuropeptides released from TRPV1-expressing afferent C fibers." (PMID 24280677, 2012). "Overexpression of FSTL1 in macrophages and fibroblasts augments the activity of proinflammatory cytokines, including interleukin (IL)-1β, tumor necrosis factor α (TNFα), and IL-6 and causes severe arthritis in the normal mouse." (PMID 21303509, 2011). "Exacerbation of the arthritis was associated with elevated systemic proinflammatory cytokines and enhanced T-helper cell 1 (Th1)-cytokine and TNF-α production by spleen cells." (PMID 21261967, 2011). "The increased levels of extra-physiologically activated TRPV1 and TRPV4 channels caused by incubation with TNF-α can significantly contribute to the activation of synoviocytes observed in joint inflammation." (PMID 19695100, 2009). "In the anti-CII antibody and LPS-induced arthritis model, arthritis development and TNF-α production were enhanced in RP105-deficient mice when a reduced dose of LPS was administered." (PMID 18847495, 2008). "To demonstrate that increased lymphangiogenesis is not limited to the arthritis in TNF-Tg mice and to determine the association between joint inflammation and lymphatic vessel formation during the course of arthritis induction, we used mice with K/B × N SIA." (PMID 17997858, 2007). "Infection of mice with a lower dose of staphylococci resulted in an overall low mortality, but the frequency of arthritis was significantly higher in the wild-type group compared with the TNF-α/LT-α-deficient mice (40% versus 13%)." (PMID 17129374, 2006). "There is also evidence that TNF inhibitors can trigger or unmask myositis in predisposed individuals: several reports detail new-onset dermatomyositis occurring after 2–6 months of etanercept or adalimumab therapy for arthritis." (PMID 40861474, 2025). "Considering the resistance of her arthritis to anti-TNF therapy, the potential pathogenic mechanism behind the disease and the existing clinical indication for JAK1/2 inhibitor for arthritis, the patient was switched to baricitinib, with a good clinical response." (PMID 41249727, 2025). "However, ETA treatment did result in lower arthritis scores, indicating that either TNF alone, as already reported, or TNF in association with LTα3 was involved in this model." (PMID 40650132, 2025). "Moreover, TNFα suppression decreased both inflammation and bone loss in murine collagen-induced arthritis." (PMID 38672734, 2024).
Arthritis (continued). "We found here that systemically administered IL-23 could elicit pain and arthritis in a mBSA-injected joint and that neutralization of TNF and deletion of Csf2 and Ccl17 prevented the pain and reduced the associated arthritis." (PMID 39107827, 2024). "It is perhaps worth noting that in two T- and B-lymphocyte-independent arthritis models in which IL-23 is induced or systemically administered there appears to be an association with the same cytokines, namely, TNF, GM-CSF and CCL17, in controlling pain and disease." (PMID 39107827, 2024). "Interestingly, in vitro treatments of joint-infiltrating neutrophils with conventional mCTLA4Ig dampened the secretion of tumor necrosis factor-α (TNF-α), a well-known pathogenic cytokine in human and mouse arthritis." (PMID 36797799, 2023). "Other authors observed that the treatment with hydroethanolic extract of the leaves of S. terebinthifolius caused a reduction in the concentration of IL-6 and TNF-α in a model of arthritis induced by zymosan in mice, which corroborates the effect observed in our study." (PMID 37639162, 2023). "Robust evidence has linked overexpression of TNF to arthritis severity in animal models." (PMID 36389831, 2022). "Interleukins and tumor necrosis factor (TNF)-α have been linked to arthritis etiology." (PMID 35242033, 2022). "Importantly, anti-TNF therapy is able to restore these PLV contractions associated with amelioration of arthritis." (PMID 35255954, 2022). "To investigate whether exacerbated arthritis symptoms were caused by enhanced TNF-α expression in CD4 T cells upon SIGIRR deficiency, we examined cytokine production in memory CD4+ T cells upon antigen immunization." (PMID 36401167, 2022). "Moreover, TIA1-KO mice develop spontaneous arthritis, associated with pathological overexpression of TNF-α." (PMID 35163320, 2022). "TIAL1-deficient mice develop arthritis and elevated TNF expression." (PMID 34578166, 2021). "TNF-α may play a central role in vascular and bone pathology and the development of arthritis-associated CVD and OP17,26." (PMID 34593938, 2021). "After adding the critical case–control samples for Asians, the TNF-α G-308A, AA genotype exhibited 2.57 times more risk of developing arthritis when compared with the GG + GA genotype (95% CI, 1.56–4.23), and the cumulative samples for TSA (n = 2182) were sufficient to obtain a definite conclusion." (PMID 34735544, 2021). "Regarding targeted therapies, several reports suggested that anti-TNF agents and other biologics may decrease arthritis-associated bone loss and suppress inflammatory atherosclerosis." (PMID 34593938, 2021). "Consequently, IgG produced by plasma cells is also decreased in Pad2-/- mice, which is associated with alleviated severity of TNF-α induced arthritis." (PMID 34804050, 2021). "In addition, arthritis-associated factors, such as TNF-α, IL-1β, NF-κB transcription activity, prostaglandin E2, matrix metalloproteinases and COX-2 expression were inhibited by curcumin treatment." (PMID 34959384, 2021). "This could cause less Noggin production by T cells in arthritis, which could lead to the unresponsiveness of rat PBMCs to TNF-α." (PMID 34830044, 2021). "TNF-α expression is upregulated in arthritis caused by LPS treatment." (PMID 32983956, 2020). "Bad loss aggravates arthritis in TNFα transgenic (TNF-Tg) mouse model." (PMID 33270017, 2020). "Furthermore, a TTP deficiency in mice causes spontaneous development of arthritis and other inflammatory syndromes, such as dermatitis and cachexia, which are mainly due to the overproduction of TNF." (PMID 32708595, 2020). "Histopathological analysis showed increased synovitis, pannus formation, as well as cartilage and bone destruction in the joints of 3-month-old TNF-Tg/Bad−/− mice compared with TNF-Tg littermates, suggesting that Bad loss also exacerbates experimental arthritis in TNF-Tg model." (PMID 33270017, 2020).
Arthritis (continued). "Furthermore, we used TNF‐α‐deficient mice and found that severity of arthritis was significantly decreased in TNF‐α‐deficient mice compared to wild‐type mice." (PMID 32994999, 2020). "In the serum transfer-induced arthritis (STIA) and TNF-transgenic model of arthritis, it could be shown that a deficiency of 11β-HSD1 leads to an increase of inflammation, suggesting attenuation of endogenous GC action." (PMID 31681333, 2019). "Together, our findings suggest that delayed and continuous TNF production in the sensorial ganglia may drive persistent joint pain after the resolution of acute inflammation associated with arthritis." (PMID 32038637, 2019). "Here, similar to CD patients, we identified female gender, older age at diagnosis, longer disease duration, IBD-related surgery, treatment with anti-TNF as well as the presence of other EIM to be independently associated with the presence of arthritis/arthralgia in the UC/IBDU." (PMID 31039159, 2019). "On the contrary, novel insights in TNF-dependent mouse models suggested that sclerostin blockade might be deleterious for arthritis since SOST deficiency worsened arthritis in the combined mouse model of SOST−/−/hTNFtg23." (PMID 29472591, 2018). "Additionally, the TNF rs1800629 variant demonstrated different drug responses to TNF-alpha inhibitors in arthritis, psoriatic arthritis, and ankylosing spondylitis." (PMID 30518145, 2018). "To investigate the effect of B cells on OBs in RA, we first examined the anatomic relationship between B cells (B220+) and OBs (osteocalcin [OCN]+) in 6-month-old TNF-Tg mice with severe arthritis and systemic bone loss, using double immunofluorescence (IF) staining on frozen sections of bone." (PMID 30510188, 2018). "We have shown previously that TNF-Tg mice with severe arthritis typically have reduced or loss of lymphatic vessel contractions and decreased lymphatic flow from inflamed joints, but the mechanisms involved are unknown." (PMID 26970913, 2016). "We carried out a computer-assisted search of PubMed for the medical literature from January 1981 to January 2015 using the keywords HIV, acquired immune-deficiency syndrome, rheumatic manifestations, arthritis, spondyloarthropathy, anti-TNF and disease modifying antirheumatic drugs." (PMID 26932524, 2016). "However, low LN PD signal at baseline despite active arthritis was strongly associated with a poor clinical response to TNF blockade." (PMID 27770827, 2016). "A recent study confirmed that the combined blockade of TNFα and IL-17A is more effective in inhibiting cytokine, chemokine, and matrix enzyme responses from human mesenchymal cells and in blocking tissue destruction associated with a mouse model of arthritis." (PMID 25904914, 2015). "In animal arthritis models, the levels of TNF-α, IL-2, and IL-10 were decreased by the HO-1 inducer cobalt protoporphyrin IX (CoPP), indicating that HO-1 deficiency causes chronic inflammatory conditions in arthritis." (PMID 25313362, 2014). "Furthermore, a number of inflammatory mediators are implicated in the establishment and progression of arthritis, including proinflammatory cytokines such as tumor necrosis factor alpha (TNFα) and interleukin (IL)-6 and IL-17." (PMID 25028072, 2014). "So we investigated whether the LPS challenge could be brought forward to a time before arthritis symptoms became manifest so that TNFα production associated with LPS challenge could be differentiated from TNFα that may be driving the arthritis." (PMID 25344414, 2014). "TNF-α acts synergistically with IL-1β in the production of matrix metalloproteinases, the expression of cell adhesion molecules and the secretion of prostaglandins and these changes result in the joint destruction that is associated with arthritis." (PMID 24940448, 2014). "Interestingly, other experimental studies have found that deficiency of TNFα was associated with more severe infection and more severe arthritis." (PMID 24995143, 2014).
Arthritis (continued). "In addition, neutralizing BLA TNF-α with Infliximab antibodies reduced anxiety-like behaviors associated to arthritis." (PMID 25408902, 2013). "They further demonstrated that mice deficient in Cryptochrome 1 and Cryptochrome 2 demonstrated arthritis aggravation, which might be due to upregulation of TNF." (PMID 22621205, 2012). "TNF-α inhibitors have been reported to cause drug-induced lupus, as well as rashes and arthritis." (PMID 23216789, 2012). "However, at day 90 after immunization, in the chronic stage of arthritis, the pro-inflammatory cytokines IL-12p70, TNF alpha and MCP-1 were suppressed in TLR4 deficient mice compared to wt mice." (PMID 21858160, 2011). "In addition, LPS is known to induce IL-1β and various other cytokines and mediators, such as TNFα and prostaglandin E2, implicated in naturally occurring arthritis." (PMID 19272138, 2009). "The purpose of the present study was to investigate whether the arthritis-inducing effect of HMGB1 is dependent on TNFα expression in vivo and to assess whether TNFα deficiency affects a proinflammatory cytokine response to HMGB1 in vitro." (PMID 18582368, 2008). "In a recent study of adjuvant induced arthritis in a rat model, arthritic changes were associated with raised levels of MMPs, IL-1β and TNF-α in joint tissue; this was ameliorated after TIMP-4 gene therapy in the treated group compared with the untreated control animals." (PMID 19088876, 2008). "The pathophysiological mechanisms of bone loss in arthritis have been shown to be mediated through the activation of osteoclasts by the macrophage-derived proinflammatory cytokines tumor necrosis factor-α and IL-1, and by the production of RANKL by activated T-lymphocytes and fibroblasts." (PMID 15987485, 2005). "Elevated expression of IL-6 and TNF-α in pericytes and smooth muscle cells indicates their involvement in inflammatory signaling and tissue remodeling within adipose stromal tissues, which may contribute to arthritis-associated inflammation." (PMID 40266392, 2025). "While anti-TNF-α drugs in the progression of kidney disease may favor deterioration of renal function, and their efficacy and safety have been demonstrated in cases of arthritis, however, it may contribute to an increased risk of lymphoma and skin cancer." (PMID 37096248, 2023). "Furthermore, mice harboring a T106M mutation in p38α resisted the drug inhibitory effect of collagen antibody-induced arthritis and LPS-induced TNF production, whereas the same mutation in p38β had the opposite effect, and p38β knockout mice responded normally to inflammatory stimuli." (PMID 24771982, 2014). "All these herbal drugs suppress the activation of nuclear factor-kB and thus lead to downregulation of the expression of TNF-α, adhesion molecules, metalloproteinase, cyclooxygenase-2, 5-lipoxygenase, and other inflammatory intermediates, all of which are associated with arthritis." (PMID 24688450, 2014). "In general, from studies using human patient data and animal models of alphaviral arthritis, acute alphaviral-induced arthritis is hallmarked by increased levels of IFNα/β, IFNγ, TNFα, IL-6, IL-1, IP-10, IL-12, IL-15 and CXCL9MCP-1 (CCL2), and MIF-I." (PMID 41442410, 2026). "Arthritis index (AI), joint histology, serum cytokines (TNF-α, IL-6, IL-17, and TGF-β), and metabolites (lactate and pyruvate) were assessed." (PMID 42260739, 2026). "Clinically, it has been demonstrated to lower serum uric acid, regulate serum IL-6, TNF-α, and erythrocyte sedimentation rate, and alleviate arthritis induced by HUA." (PMID 41024187, 2025). "The anti-TNF/IL-6 bispecific antibody completely inhibits the inflammatory factor CXCL13 in the arthritis model, and its effect is superior to that of the monoclonal antibody combination." (PMID 40932933, 2025). "Infliximab, a TNF-alpha inhibitor, has been widely used in various manifestations, including ocular, enteric, neuro, vasculitis, and arthritis." (PMID 40539167, 2025).
Arthritis (continued). "Following arthritis induction, an increased immunoexpression of TNF‐α and IL‐17 was observed in the synovial membrane and articular cartilage." (PMID 41006957, 2025). "In a mouse model of arthritis, we observed strong TNF production by both Tconvs and Tregs during the chronic but not the acute phase of the disease." (PMID 40977146, 2025). "Due to the challenges associated with obtaining synovial tissue samples from patients, we employed a human tumor necrosis factor-alpha (TNF-α) transgenic (TgTC) mouse model of arthritis as an experimental surrogate." (PMID 40787440, 2025). "For example, dual inhibition of VEGF and TNF-α pathways has shown synergistic effects in reducing inflammation and tissue damage in experimental models of arthritis." (PMID 40487799, 2025). "In arthritis studies, a hydroalcoholic extract of Moringa flowers significantly reduced the levels of rheumatoid factor, TNF-α, and IL-1 in arthritic rats, suggesting its effectiveness in arthritis treatment." (PMID 40703714, 2025). "SADS alleviated the progression of experimental arthritis in a RA mouse model by modulating the TNF-α and RAGE signaling pathways, supporting its potential as a therapeutic agent for RA." (PMID 40688514, 2025). "Anti TNF therapy ameliorates arthritis by restoring lymphatic transport and relieving physical lymphatic obstruction by immune cells." (PMID 41227037, 2025). "Cytokines such as TNF-α, IL-1β, and IL-6 induce joint inflammation and upregulate the production of MMPs (1, 2, 3, 7, 8, 9, and 13) through inflammatory signaling." (PMID 40427394, 2025). "Delanzomib decreased the severity of arthritis and reduced the levels of TNFα, IL-6, and CRP in rats with CIA." (PMID 40243560, 2025). "Preclinical studies demonstrate its potent anti-inflammatory effects by inhibiting prostaglandin E2 synthesis and modulating cytokines like TNF-α and IL-6, suggesting applications for chronic inflammatory disorders such as arthritis." (PMID 40870742, 2025). "TNF transgenic (TNF-Tg) mice overexpress human TNF-α, leading to spontaneous arthritis similar to human RA." (PMID 41019075, 2025). "Two well-established factors in the etiopathogenesis of arthritis are tumor necrosis factor-alpha (TNF-α) and interleukin-6 (IL-6), two key pro-inflammatory cytokines involved in immune-mediated diseases." (PMID 40289148, 2025). "One study previously reported the anti-inflammatory effect of rutin, which showed that rutin reduced neutrophil recruitment, joint edema, mechanical hypernociception, and articular TNF-α synthesis in murine zymosan-induced arthritis." (PMID 39906613, 2025). "The rams with arthritis showed significantly greater levels of gene expression for the genes IL-1α, IL-1β, IL-6, IL-10, TNFα, NCF4, NFKB, TMED, FCAMR, iNOS and COX18 than did the healthy rams." (PMID 40005882, 2025). "We identified a TNF + PGE2 (TP) induced gene expression signature that is enriched in IL1β+ RA and ICI-arthritis monocytic subsets, and includes genes in pathogenic IL-1, Notch and neutrophil chemokine pathways." (PMID 40662950, 2025). "We took advantage of a previous report of TNFko/ko mice exhibiting significant K/BxN arthritis that was only partially dependent on TNF." (PMID 40650132, 2025). "Similarly, targeting TNF-α can increase the risk of tuberculosis; anti-IL-23 drugs may cause hidradenitis suppurativa or arthritis; and medications, such as adalimumab (anti-TNF-α), secukinumab (anti-IL-17), and ustekinumab (anti-IL-23), can contribute to the development of thrombocytopenia." (PMID 39993340, 2025). "In CIA-induced arthritis, cartilage destruction and bone erosion were reduced by decreased protein levels of TNF-α, IL-1β, IL-6, iNOS, COX2, MMP-1, and MMP-3 in ankle joint tissue." (PMID 40725063, 2025). "Intriguingly, while IL-6 neutralization ameliorates arthritis, TNF blockade shows inconsistent therapeutic efficacy." (PMID 41583484, 2025).